HTRA1 (HtrA serine peptidase 1)
Diseases named in the same sentence as HTRA1 in open-access papers (continued):
Sharing a sentence is not in itself a finding about the gene and the disease.
CARASIL (continued). "The pathogenesis of CARASIL is related to homozygous or compound heterozygous mutations, which ultimately lead to the functional impairment of HTRA1." (PMID 37799144, 2023). "A genetically induced loss of HTRA1 function in humans is associated with cerebral autosomal-recessive arteriopathy with subcortical infarcts and leukoencephalopathy (CARASIL), a rare, hereditary form of brain microvascular disease." (PMID 39081996, 2023). "Some critical heterozygous mutation sites in HTRA1 such as p.G283E, p.P285L, p.T319I, and p.R302Q present mild to severe symptoms of CARASIL." (PMID 37009886, 2023). "Cerebral autosomal recessive arteriopathy with subcortical infarcts and leukoencephalopathy (CARASIL) is a rare inherited cerebral small vessel disease (CSVD) which is associated with mutations of the high-temperature requirement serine peptidase A1 (HTRA1) gene." (PMID 37799144, 2023). "Homozygous or compound heterozygous mutations of HTRA1 gene are considered to cause cerebral autosomal recessive arteriopathy with subcortical infarcts and leukoencephalopathy (CARASIL)." (PMID 36035189, 2022). "To date, at least 22 mutations in HTRA1 have been identified to cause cerebral autosomal recessive arteriopathy with subcortical infarcts and leukoencephalopathy (CARASIL) in an autosomal recessive form." (PMID 34551193, 2021). "CARASIL is a single-gene disorder directly affecting the cerebral small blood vessels that is caused by mutations in the HTRA1 gene encoding HtrA serine peptidase / protease 1 (HTRA1)." (PMID 34946804, 2021). "HTRA1 disorder caused by biallelic pathogenic variants (i.e., the classic CARASIL phenotype) is inherited in an autosomal recessive manner." (PMID 34946804, 2021). "In a case report study, a homozygous variant of c.847G>T in the HtrA serine protease 1 (HTRA1) gene was found in a patient with symptoms of Cerebral autosomal recessive arteriopathy with subcortical infarcts and leukoencephalopathy (CARASIL) and WMHs in MRI." (PMID 33352859, 2020). "CARASIL is a rare genetic disorder characterized by mutations in the HTRA1 gene located on chromosome 10q (10q25.3-q26.2)." (PMID 31484286, 2019). "The diagnosis of CARASIL was confirmed through molecular genetic testing, which identifies characteristic mutations in the HTRA1 gene." (PMID 31484286, 2019). "Homozygous mutations of human HTRA1 cause cerebral autosomal recessive arteriopathy with subcortical infarcts and leukoencephalopathy (CARASIL)." (PMID 29768431, 2018). "Another monogenic form of SVD is cerebral autosomal recessive arteriopathy with subcortical infarcts and leukoencephalopathy (CARASIL), caused by a loss of function mutation in the gene HtrA serine peptidase 1 (HTRA1)." (PMID 28202749, 2017). "Cerebral autosomal recessive arteriopathy with subcortical infarcts and leukoencephalopathy (CARASIL) is a hereditary cerebral small vessel disease caused by mutation of high-temperature requirement A serine peptidase 1 (HTRA1), being extremely rare and identified mainly in East Asia." (PMID 38254727, 2024). "As a hereditary disease, cerebral autosomal recessive arteriopathy with sub-cortical infarcts and leukoencephalopathy (CARASIL) has been identified to contain mutations within the HTRA1 gene, which results in the loss of HtrA1 protein or reduced protease activities." (PMID 34639128, 2021). "The increased plasma levels of HTRA1 acquire an intriguing meaning if we consider that the HTRA1 gene represents the genetic cause of cerebral autosomal recessive arteriopathy with subcortical infarcts and leukoencephalopathy (CARASIL)." (PMID 33464533, 2021). "TGFβ is a protein related to hereditary SVDs39 such as CARASIL, caused by HTRA1 gene mutations." (PMID 33767277, 2021). "Mutations in HTRA1 is known to cause CARASIL, a recessive form of hereditary small vessel disease." (PMID 32188464, 2020).
CARASIL (continued). "CARASIL is associated with mutations in HTRA1, but the characteristic extraneurologic symptoms of CARASIL, including alopecia, were lacking in this pedigree; more importantly, the genetic pattern in this pedigree did not conform to autosomal recessive inheritance." (PMID 32239807, 2020). "Moreover, mutations in HTRA1 are the cause of the hereditary small vessel disease CARASIL (cerebral autosomal recessive arteriopathy with subcortical infarcts and leukoencephalopathy)." (PMID 29860944, 2018). "This physical interaction could be abolished by the missense mutations of HtrA1 found in patients with cerebral autosomal recessive arteriopathy with subcortical infarcts and leukoencephalopathy (CARASIL)." (PMID 25506911, 2014). "Cerebral autosomal recessive arteriopathy with subcortical infarcts and leukoencephalopathy (CARASIL) is a cerebral small vessel disease accompanied by alopecia and spondylosis caused by mutations in the HTRA1 gene." (PMID 22436252, 2012). "Humans with loss-of-function mutation in HTRA1 develop cerebral autosomal recessive arteriopathy with subcortical infarcts and leukoencephalopathy (CARASIL) syndrome accompanied by non-hypertensive cerebral small blood vessel ischemia and spondylosis." (PMID 30854478, 2019). "A number of different genes come under the umbrella term of vascular leukoencephalopathies, including NOTCH3 (CADASIL), HTRA1 (cerebral autosomal recessive arteriopathy with subcortical infarcts and leukoencephalopathy (CARASIL)), CTSA (CARASAL), COL4A1 and TREX1." (PMID 30467211, 2019). "Interestingly, it has been shown that the activity of HTRA1, which is impaired in cerebral autosomal recessive arteriopathy with subcortical infarcts and leukoencephalopathy (CARASIL) patients, affects TGF-β signaling." (PMID 29269789, 2017). "Htra1 mutations resulting in HTRA1 dysfunction cause the CSVD cerebral autosomal recessive arteriopathy and subcortical infarcts and leukoencephalopathy (CARASIL), and elevation of HTRA1 in human CAA cases has been suggested as a possible marker of CAA29,30." (PMID 38600214, 2024). "Homozygous or compound heterozygous mutations in the high-temperature requirement A serine protease 1 gene (HTRA1) elicits cerebral autosomal recessive arteriopathy with subcortical infarcts and white matter lesions (CARASIL)." (PMID 36619910, 2022). "Other rare forms of monogenic vascular dementia include the recessive disorder cerebral autosomal recessive cerebral arteriopathy with subcortical infarcts and leukoencephalopathy (CARASIL), caused by mutations in HTRA1 (HtrA Serine Peptidase 1)." (PMID 35976293, 2022). "Although patients with heterozygous HTRA1-related CSVD (symptomatic carriers) are reported to have a milder form of CARASIL, little is known about the clinical and genetic differences between the two diseases." (PMID 32719647, 2020). "Impaired TGF-β signaling, due to a lack of LTBP-1 processing by HtrA1, is thought to promote the pathogenesis of CARASIL, but the underlying molecular mechanisms are not fully understood." (PMID 34946804, 2021). "It is commonly recognized that the CARASIL disease is caused by the mutation of the HTRA1 allele, whereas heterozygous mutations are not pathogenic." (PMID 29561953, 2018). "HTRA1 has been demonstrated to inhibit TGF-ß1 signaling in neuronal cells and is associated with cerebral autosomal recessive arteriopathy with subcortical infarcts and leukoencephalopathy (CARASIL)." (PMID 21829675, 2011). "CADASIL is also an inherited CSVD with similar clinical findings to heterozygous HTRA1-related CSVD and CARASIL." (PMID 37009886, 2023).
Leukoencephalopathy (26 papers, 2014 to 2025). This term describes abnormality of the white matter of the cerebrum resulting from damage to the myelin sheaths of nerve cells. "These include CADASIL (due to mutations in the NOTCH3 gene) and CARASIL (cerebral autosomal recessive arteriopathy with subcortical infarcts and leukoencephalopathy, due to mutations in the HTRA1 gene)." (PMID 37396778, 2023). "HTRA1 is a homotrimeric protease that has been implicated in vascular health since its discovery as the causal gene for cerebral autosomal recessive arteriopathy with subcortical infarcts and leukoencephalopathy, a cerebrovascular arteriopathy caused by biallelic loss-of-function variants in HTRA1." (PMID 41190437, 2025). "A similar phenomenon may be observed in autosomal recessive mutations in the HTRA1 gene, which causes Cerebral Autosomal Recessive Arteriopathy with Subcortical Infarcts and Leukoencephalopathy (Cerebral autosomal recessive arteriopathy with subcortical infarcts and leukoencephalopathy - CARASIL)." (PMID 36533159, 2022). "All HTRA1 cases were heterozygous, and no homozygous cases of cerebral autosomal recessive arteriopathy with subcortical infarcts and leukoencephalopathy were found." (PMID 39082428, 2024). "Klüver-Barrera staining, which stains myelin blue, did not reveal signs of leukoencephalopathy in the HtrA1-/- mouse brain." (PMID 29768431, 2018).
cerebral small vessel disease (24 papers, 2018 to 2025). Cerebral small vessel disease is the term currently used to pathological processes that affect the brain parenchymal circulation (arterioles, capillaries, and veins). "Recently, it was reported that several heterozygous mutations in HTRA1 also cause cerebral small vessel disease (CSVD)." (PMID 32719647, 2020). "In addition, HTRA1, a causative gene for cerebral small-vessel disease, was upregulated in HUVEC co-cultured (65 days) organoids." (PMID 37940920, 2023). "Moreover, Htra1 has been reported to modulate cerebrovascular disorder, such that its mutation is correlated with cerebral small vessel disease, and it is abnormally expressed in astrocytes to regulate astrocyte injury and development." (PMID 35549989, 2022). "For patients carrying variants outside EGFr region, no potential pathogenic mutation were identified in several other genes known to be common causal of cerebral small-vessel disease or vascular dementia (HTRA1, TREX1, COL4A1, COL4A2, GLA, APP, and ITM2B) by targeted next-generation sequencing." (PMID 34335700, 2021). "Moreover, a significant association was observed between HTRA1 rs2293871 and cerebral small vessel disease in the elderly." (PMID 34551193, 2021). "Thus, the CADASIL-like family disease may be caused by heterozygous HTRA1 gene mutation, which leads to autosomal dominant hereditary cerebral small vessel disease." (PMID 29561953, 2018). "The present study identified a total of 22 patients with mutations in NOTCH3, HTRA1, and COL4A1, which are known to cause cerebral small vessel disease (SVD)." (PMID 37237429, 2023). "HTRA1 disorder includes two phenotypes—classic CARASIL and HTRA1 cerebral small vessel disease (HTRA1-CSVD)." (PMID 34946804, 2021). "CADASIL (NOTCH3), CARASIL (HTRA1), 6p25 deletion syndrome, cerebral small-vessel diseases (FOXC1 and PITX2) are the typical entities within this group." (PMID 32849169, 2020). "We and others have shown that higher cerebral small vessel disease is strongly associated with lower processing speed; thus it is possible that higher IMF leads to higher levels of the myokine HTRA1, this in turn drives cerebral small vessel disease, manifesting as slower processing speed." (PMID 39974123, 2025). "Several HTRA1 mutations have been associated with cerebral small vessel disease in humans, but these studies did not test associations with cognitive function." (PMID 39974123, 2025). "Cerebral small vessel disease (CSVD), often causing stroke, is characterized by young adult onset and is considered to be caused by variants in the high temperature-demanding serine peptidase A1 (HTRA1) gene." (PMID 39272661, 2024). "The majority of patients with cerebral small vessel disease, which is highly prevalent in the elderly population, do not harbor known pathogenic variants in HTRA1 or other genes." (PMID 39013852, 2024). "Therefore, loss-of-function mutation HTRA1 results in the stimulation of TGF-β signaling, which is considered to be a key pathophysiological mechanism of CARASIL and HTRA1-related cerebral small vessel disease." (PMID 38254727, 2024). "In addition, high-temperature requirement protein A1 (Htra1) is an evolutionarily conserved extracellular serine protease, which has been well-identified in brain disorders, including cerebral small vessel disease and cerebral autosomal recessive arteriopathy." (PMID 35549989, 2022). "Summary of pathological findings in HTRA1-related cerebral small vessel disease cases." (PMID 32719647, 2020). "Disruption of the vascular ECM has been hypothesised to be a key component in pathogenesis of cerebral small vessel disease, particularly in monogenic forms, and several of the genes implicated in this study (COL4A2, LOX, SH3PXD2A, GPR126, HTRA1) have key roles in the ECM." (PMID 33773637, 2021).
cerebral small vessel disease (continued). "The presence of both rare and common risk variants in HTRA1 points to it being a key molecule in lacunar stroke pathogenesis, and is a feature shared with another gene identified in this study, COL4A2, in which rare variants also cause monogenic forms of cerebral small vessel disease." (PMID 33773637, 2021). "Studies have shown that HTRA1 can promote transforming growth factor (TGF)β1 signaling by cleaving latent TGFβ-binding protein, which directly contributes to the occurrence of cerebral small vessel disease and scar activation." (PMID 38515161, 2024).
Stroke (24 papers, 2019 to 2025). Sudden impairment of blood flow to a part of the brain due to occlusion or rupture of an artery to the brain. "While loss-of-function variants in HTRA1 are known to cause monogenic stroke syndromes, we found that damaging missense variants in HTRA1 are associated with increased risk of disease in both the cerebrovascular and coronary circulation." (PMID 41190437, 2025). "We established a hiPSC line derived from a female patient carrying a heterozygous R302Q mutation in HTRA1 with clinical manifestations of CSVD such as stroke, dementia, multiple lacunar infarcts, and cervical spondylosis." (PMID 37009886, 2023). "detected only three cases with pathogenic variants in other monogenetic diseases causing stroke (HTRA1, COL4A1) apart from NOTCH3." (PMID 36411388, 2023). "We hereby explored the association between blood-based HTRA serine protease 1 (HTRA1) methylation and the risk of stroke." (PMID 36581876, 2022). "This blood-based HTRA1 methylation was associated with stroke independently from the known risk factors and mostly affected the older population." (PMID 36581876, 2022). "This further supported that a later onset age of stroke and cognitive decline (mainly at the fifth to sixth decade of life) were the main features of HTRA1-associated dominant CSVD." (PMID 36035189, 2022). "The presence of an HTRA1 variant was associated with increased risk of migraine with aura (OR, 10.36; 95% CI, 3.89-21.89; P = 7.6 × 10−5), any stroke (OR, 1.86; 95% CI, 1.30-2.59; P = .001), and ischemic stroke (OR, 2.01; 95% CI, 1.27-3.00; P = .004)." (PMID 36300346, 2022). "Age was reported to play an essential role in the pattern of DNA methylation; we therefore evaluated the association between HTRA1 methylation in the blood and stroke stratified by two major age groups (< 70 and ≥ 70 years)." (PMID 36581876, 2022). "We extended this finding to show similar effects in HTRA1 where the p.Arg227Trp variant was found to have lower stroke risk." (PMID 36300346, 2022). "Among stroke and dementia cases, 0.09% of strokes and 0.14% of vascular dementias were attributed to HTRA1 variants." (PMID 36300346, 2022). "This observed HTRA1 methylation-related risk of stroke was still based on a relatively small sample size." (PMID 36581876, 2022). "Compared with other HTRA1 carriers, p.Arg227Trp carriers had reduced risk of any stroke (OR, 0.39; 95% CI, 0.20-0.79; P = .01) and ischemic stroke (OR, 0.28; 95% CI, 0.11-0.65; P = .003)." (PMID 36300346, 2022). "Interestingly, lower genetically determined HTRA1 plasma protein levels were also associated with higher risk of stroke (any, ischemic) and AD at p < 0.05." (PMID 39011113, 2024). "Another 51-year-old woman with CADASIL syndrome of stroke and mild dementia carried heterozygous HTRA1 p.G276A, which was reported to be likely pathogenic to cerebral autosomal dominant arteriopathy with subcortical infarcts and leukoencephalopathy type 2 (CADASIL2)." (PMID 36580209, 2023). "Our previous study also showed that HTRA1 variants might confer the genetic susceptibility to stroke." (PMID 36581876, 2022). "In our study, altered HTRA1 methylation was associated with stroke at clinical and preclinical stages and thus may provide a potential biomarker in the blood for the risk evaluation and preclinical detection of stroke." (PMID 36581876, 2022). "Strong correlations have been found at the COL4A1/2, FOXC1FOXC1, and HTRA1 loci—genes essential in preserving the integrity of the cerebral microvasculature—indicating that small-vessel (lacunar) stroke is genetically unique." (PMID 40863347, 2025). "In fact, two of these proteins showed significant associations with stroke or dementia (FBLN3, HTRA1) in consistent direction and three were located within cSVD GWAS loci (FBLN3, HTRA1, NMT1), supporting the robustness of these findings." (PMID 41266628, 2025).